UXT-AS1 (UXT antisense RNA 1)
Gene: Long non-coding RNA gene on chromosome X (47,658,833 to 47,692,326, forward strand). Ensembl gene ENSG00000267064.
Diseases named in the same sentence as UXT-AS1 in open-access papers:
UXT-AS1 is named in the same sentence as 2 diseases in open-access papers, as found by Europe PMC text mining. Sharing a sentence is not in itself a finding about the gene and the disease.
UXT-AS1 shares sentences with these, for which no sentence is quoted: cancer (1 paper); pancreatic ductal adenocarcinoma (1).